LCE3E (late cornified envelope 3E)
Description:
Precursors of the cornified envelope of the stratum corneum.
Synonyms: LEP17
Tractability: No criterion of Open Targets' tractability assessment is met for any kind of drug.
Gene: Protein-coding gene on chromosome 1 (152,565,654 to 152,566,780, reverse strand). Ensembl gene ENSG00000185966.
Pathways (Reactome):
Developmental Biology: Formation of the cornified envelope
Gene Ontology:
Molecular function: protein binding
Biological process: epidermis development
Genetic constraint (gnomAD): Loss-of-function variants: 1 observed, 1.36 expected, observed/expected ratio (o/e) 0.74, 90% interval 0.22 to 1.86. That is too few expected variants to judge how well the gene tolerates losing a copy. Missense variants: 133 observed, 122.41 expected, observed/expected ratio (o/e) 1.09, 90% interval 0.94 to 1.25. Synonymous variants: 40 observed, 48.98 expected, observed/expected ratio (o/e) 0.82, 90% interval 0.63 to 1.06.
Homologues: Orthologues: chimpanzee LCE3E (97% identical). Paralogues in human: LCE3D (96% identical), LCE3C (83% identical), LCE3B (79% identical), LCE3A (76% identical), LCE2C (64% identical), LCE2D (63% identical), LCE5A (63% identical), LCE2A (62% identical), LCE2B (62% identical), LCE1E (60% identical), LCE1F (59% identical), LCE1D (55% identical), and 8 more.
Diseases named in the same sentence as LCE3E in open-access papers:
LCE3E is named in the same sentence as 7 diseases in open-access papers, as found by Europe PMC text mining. Sharing a sentence is not in itself a finding about the gene and the disease. The quoted sentences say what the papers report.
psoriasis (3 papers, 2018 to 2023). An autoimmune condition characterized by red, well-delineated plaques with silvery scales that are usually on the extensor surfaces and scalp. "These genes include genes that are well known to be involved in psoriasis, including LCE3D, LCE3E, SERPINB4, and S100A7A, genes involved in activation and proliferation of keratinocytes, modulation of host immune response, and antimicrobial defense." (PMID 30054515, 2018).
esophageal cancer (1 paper, 2024). A primary or metastatic malignant neoplasm involving the esophagus. "According to xiantao database, PPL, PI3, LCE3E, and TGM1 were more expressed in esophageal cancer than normal tissues (p < .05)." (PMID 38241178, 2024).
Hyperkeratosis (1 paper, 2021). Hyperkeratosis is a histopathological term defining a thickened stratum corneum and may be present in many different skin conditions, with many possible overlaps. "The overlapping DEGs included genes associated with hyperkeratosis (upregulated LCE3E and TMEM45A), wound healing (upregulated KRT17, IL36G, TNC, and TGFBI), barrier defects (downregulated FRAS1 and BCL11A), and response to infection (upregulated IL36G, ADAP2, DFNA5, RFTN1, LITAF, and TMEM173)." (PMID 34506598, 2021).
plantar wart (1 paper, 2017). A wart in the plantar surface of the foot. "For example, two genes involved in innate immunity of skin, LCE3E and DSG1, were significantly associated with plantar warts and yeast infections, respectively." (PMID 28928442, 2017).
LCE3E also shares sentences with these, for which no sentence is quoted: infection (1 paper); Obesity (1); overnutrition (1).